TLR4 (toll like receptor 4)
Diseases named in the same sentence as TLR4 in open-access papers (continued):
Sharing a sentence is not in itself a finding about the gene and the disease.
Sepsis (continued). "Extracellular HMGB1 and its receptors, RAGE, TLR2, and TLR4, have been implicated in mechanisms of many inflammatory diseases, including sepsis, atherosclerosis, and rheumatoid arthritis by induction of senescence-associated secretory phenotype via NF-kB activation." (PMID 33384655, 2020). "We therefore postulated that RSV-induced autophagy may play a role that intersects with TLR4 signaling components to regulate systemic inflammation associated with sepsis." (PMID 33139717, 2020). "We found that AML patients who have TLR2 Arg753Gln: AG genotypes and A allele; TLR4 Asp299Gly: CT genotype and C allele; TLR4 Thr399Ile AG genotype and A allele showed significant higher association to sepsis and pneumonia as compared to other genotypes and alleles." (PMID 33247673, 2020). "Taken together, upregulation of TLR4 in the CD38−/− mice could cause an aggravated kidney injury in sepsis induced by LPS through promotion of the IFN-γ expression." (PMID 30915370, 2019). "In this scenario, deficient TLR4 activation in the obese individuals may help to contain the overstimulation and the “cytokine storm” caused by sepsis, improving prognosis and lifespan of obese patients." (PMID 30510205, 2018). "In human sepsis, the mechanisms underlying renal dysfunction remain unknown, and so is the exact role of LPS mediated TLR4‐activation." (PMID 27602552, 2017). "E. rhusiopathiae could induce cytokines mainly via the TLR4 pathway, and high levels of cytokines and toxins secreted by bacteria could eventually destroy deep tissues and cause septicemia." (PMID 28976997, 2017). "Sexual dimorphism in the expression of TLR4 for bacterial LPS in murine macrophages has been reported, and TLR4 might contribute to the greater susceptibility of males to bacteria sepsis." (PMID 28912808, 2017). "The improper regulation of LPS/TRL4 signaling has the potential to induce massive inflammation and cause acute sepsis; therefore, it is important to further explore and evaluate the molecules which might be involved in the regulation of TLR4 signaling." (PMID 27563672, 2016). "Additionally, consequent screening removed 86 more reports for not concerning on the association between the polymorphism rs4986790 or rs4986791 of toll like receptor 4 and sepsis and insufficient data." (PMID 27958344, 2016). "While hemolysis in patients with sepsis is associated with increased mortality its mechanisms are unknown and Toll-like receptor (TLR)-4 mediated effects, complement-mediated hemolysis, or direct cell membrane effects are all conceivable mechanisms." (PMID 27759044, 2016). "TLR2 or TLR4-deficient mice are more resistant to polymicrobial sepsis." (PMID 26147469, 2015). "In the present study, we have investigated the effects of preventive and therapeutic administration of anti-TLR2 and anti-TLR4 mAbs, either alone or in combination, and in conjunction with antibiotic treatment in a model of polymicrobial sepsis caused by cecal ligation and puncture (CLP)." (PMID 26147469, 2015). "In CLP-treated septic mice, p38 MAPK inhibitor (SB203580) significantly inhibited high mobility group box 1 (HMGB-1) release and increased survival rate, HMGB-1 is an endogenous ligand for TLR4, in addition to LPS, and an important mediator of sepsis-associated death in experimental studies." (PMID 26063982, 2015). "Moreover, sepsis and septic shock by induced LPS resulted in severe lung inflammation in Nrf2-deficient mice through the TLR4 signaling pathway." (PMID 24624340, 2014). "In addition to being responsible for fever and diarrhea, the TLR4 activation caused by endotoxin with subsequent cytokine production can lead to life-threatening syndromes such as sepsis and septic shock." (PMID 24602493, 2014). "Platelet TLR4 expression is associated with sepsis and thrombocytopenia." (PMID 24489676, 2014).
Sepsis (continued). "The observed association of higher susceptibility to sepsis among TLR4 rs11536889 and CD14 rs2563298 genotypes may help intensive care specialists to identify patients at risk of developing sepsis." (PMID 25394369, 2014). "A possible limitation of this study is the possibility that the studied TLR4 rs11536889 SNP associated with organ failure in patients with sepsis is in linkage disequilibrium with SNPs in another nearby gene and that these latter genes are responsible for the observed phenotypic effects." (PMID 24950711, 2014). "However, genetic variation in TLR4 that modulates inflammatory response and sepsis has been associated with reduced risk of atherosclerosis and CVD supporting the relevance of modeling acute TLR4 signaling responses to risk of chronic cardiometabolic disease." (PMID 23497455, 2013). "Furthermore, T2.5 used in combination with the 1A6 anti-TLR4/MD-2 antibody and antimicrobial therapy protected mice from sepsis caused by S. enterica and E. coli." (PMID 24302927, 2013). "The +896 A→G nonsynonymous single-nucleotide polymorphism of the TLR4 gene, causing the Asp299→Gly change in the extracellular domain of TLR4, attenuates receptor signalling, decreases endotoxin responsiveness, and determines poor outcomes from sepsis." (PMID 21912565, 2012). "Conversely the fate of other membrane molecules, e.g. toll-like receptor 4 (TLR4), which is usually associated with infection and sepsis and recently has been linked to hemorrhagic shock and intestinal ischemia, remains unknown." (PMID 22768227, 2012). "Particularly, considering the fact that TLR4 SNP carriers demonstrate a higher risk for developing sepsis, that is, the frequency of TLR4 SNP carriers in a septic patient cohort is higher (approximately 20%) compared to the normal population or, for example, cardiac surgical patients." (PMID 21466684, 2011). "Because cDCs exhibit functional defects following hemorrhage, the TLR4 agonist MPLA may also be a good candidate for treating post hemorrhage susceptibility to sepsis." (PMID 20949109, 2010). "However, in individuals bearing the Asp299Gly TLR4 haplotype alone an altered cytokine response to LPS and increased susceptibility for sepsis has been reported." (PMID 20525286, 2010). "The central role of TLR2 and TLR4 in microbial responses suggests that they may be implicated in the pathophysiology and the outcome of human sepsis." (PMID 19371402, 2009). "Causative factors might be the release of cytokines during sepsis like IL-6, which has been shown to upregulate TLR4 on human monocytes." (PMID 19371402, 2009). "Notably, carriers of the TLR4 rs4986790 mutation exhibited increased risk of severe infections and prolonged hospital stays, while IL-10 rs1800896 was linked to higher complication rates, particularly respiratory failure and sepsis." (PMID 40692949, 2025). "LPS activation of TLR4 at the site of infection is a generally beneficial response, leading to pathogen clearance; however, if the infection is not sufficiently controlled, bacteria and LPS can make their way into circulation, causing sepsis and/or endotoxemia." (PMID 40512027, 2025). "Thus, interventional measures targeting the TLR4 signaling pathway may emerge as novel strategies for the prevention and treatment of sepsis-associated liver injury." (PMID 40072101, 2025). "Moreover, Rab5a and membrane TLR4 expressions were positively associated with the Sequential Organ Failure Assessment score of sepsis patients, and more importantly, the septic non-survivors had significantly increased Rab5a mRNA levels when compared to the septic survivors." (PMID 38549133, 2024). "Mutations in TLR-4 are associated with differences in lipopolysaccharide (LPS) responsiveness in humans, implying that host response to infections may be variable, rendering some to develop sepsis, while others may be resistant." (PMID 37759732, 2023).
Sepsis (continued). "However, excessive activation of TLR4 induced by LPS leads to substantial release of pro-inflammatory factors, which may bring a cytokine storm in the body and cause severe sepsis." (PMID 35281916, 2022). "Furthermore, data from a sepsis/ARDS rodent model suggests that inhibition of TLR4 signaling pathway may relieve sepsis-associated ARDS in through regulating macrophage activation and the inflammatory response." (PMID 35770004, 2022). "Consequently, many studies have been conducted all over the world to reveal the prevalence of these SNPs and their impact on infection and sepsis susceptibility, but a varied pattern of prevalence was found for both TLR4 and TLR2 SNPs among different populations." (PMID 36142893, 2022). "Irisin causes a decrease in TLR4 and MyD88 levels, which could prevent the development of sepsis." (PMID 35784579, 2022). "Meanwhile, the conducted pilot study concluded that the TLR2 genotype may be a risk factor for sepsis in adult patients, Moreover, our study showed that Asp299Gly polymorphism in TLR4 may be associated with an increased risk of Acinetobacter baumannii infection." (PMID 36142893, 2022). "Furthermore, LPS causes septic cardiomyopathy via TLR4 activation, which is of relevance since sepsis—whether viral or bacterial—is implicated in severe cases of COVID-19." (PMID 33505220, 2021). "However, excessive TLR4 activation orchestrated by elevated concentrations of LPS could be detrimental, leading to sepsis, a life-threatening organ dysfunction caused by the dysregulated host response to infection." (PMID 34757442, 2021). "Because TLR4 activation by ligands such as LPS was one of the dominant causes for severe sepsis in bacterial infection, and TLR4 inhibition by TAK-242 alleviated fatal infection by MHV-A59, we reasoned that ACSL1 upregulation may be the consequence of TLR4 signaling activation." (PMID 34960652, 2021). "Moreover, the roles of sesamin in regulating TLR4-associated signalling during the progression of sepsis-induced injury indicate that TLR4 may be a potential pharmaceutical target for the clinical treatment of sepsis in the future." (PMID 32893702, 2020). "However, low bacteremia and a high survival rate in TLR4-deficient mice with lethal polymicrobial sepsis were reported in another study, indicating the harmful role of TLR4 signaling in severe polymicrobial sepsis." (PMID 29977913, 2018). "Therefore, in the TLR4-deficient mouse septicemia model, there may be other receptors involved, so that the vaccine can still induce a certain protective effect." (PMID 28659923, 2017). "Thus, platelet TLR4 is implicated in sepsis because of these events." (PMID 28976997, 2017). "Although full activation of TLR4 pathway is essential for initiating the innate immune response and enhancing adaptive immunity to eliminate invading microbial pathogen, excessive activation of TLR4 signaling may cause immune disorders such as inflammatory disease and sepsis shock." (PMID 26785354, 2016). "In addition to regular predictive factors such as malnutrition, high plasma endotoxin and sCD14 levels for development of severe sepsis in high risk groups, the novel predictive factors were either single or double TLR4+896A/G and CD14-159C/T variant alleles carriers observed in current study." (PMID 27861595, 2016). "Further supporting this hypothesis, it is well known that TLR2 and TLR4 are crucial in host defense against several bacterial pathogens that, like B. microti, cause sepsis like Staphylococcus aureus, Streptococcus pneumoniae, Klebsiella pneumoniae, Haemophillus influenza and Acinetobacter baumanii." (PMID 28119856, 2016). "In line with previous studies, carriers of variant allele of TLR4 +896A/G in our febrile acute de-compensated cirrhotic patients did show increased LPS-stimulated IL-10 production and complicated with higher frequency (59%) of severe sepsis compared to wild-type allele carriers (32%)." (PMID 27861595, 2016).
Sepsis (continued). "The ability of TLR4 to respond to a particular LPS species is important since insufficient activation may not prevent bacterial growth while excessive immune reaction may lead to immunopathology associated with sepsis." (PMID 26635809, 2015). "Serum levels of TLR2, TLR4, TLR9, IL-1β, IL-6, IL-8, IL-10, TNF-α and IFN-γ were quantified by enzyme-linked immunosorbent assay at the time of sepsis diagnosis." (PMID 41846925, 2026). "Together, these data suggest that L-carvone modifies the TLR4/NF-κB/iNOS/NO axis, thus restoring redox balance and renal micro-dynamics during sepsis." (PMID 41585603, 2026). "Toll-like receptor 4 plays a central role in pathogen recognition and inflammatory signalling and has been considered a key driver of sepsis pathophysiology." (PMID 42218524, 2026). "Animals treated with L-carvone at all three doses showed markedly lower TLR4 mRNA levels than observed in the sepsis model group." (PMID 41585603, 2026). "The excessive TLR4 signaling promotes a failure of neutrophil recruitment to infected tissues due to CXCR2 internalization during sepsis." (PMID 40241761, 2025). "highlighted TLR4 as the key LPS receptor activating immune responses, with significantly higher activation rates observed in sepsis patients compared to healthy individuals, offering prospects for targeted therapy based on TLR-4 activation status." (PMID 40386784, 2025). "Specifically, we show that isaridin E attenuates LPS-driven inflammatory responses in vascular and pulmonary tissues by disrupting the TLR4/NF-κB signaling cascade, a pivotal pathway in the pathogenesis of sepsis and other inflammatory diseases." (PMID 40278266, 2025). "For instance, lncRNA NEAT1 increases the inflammatory response in sepsis-induced liver injury by regulating the Let-7a/TLR4 (Toll-like receptor 4) signaling pathway." (PMID 39067063, 2025). "In a model of sepsis, nicotine inhibits Toll-like receptor 4 (TLR4) (LPS)-mediated inflammation and decreases the production of pro-inflammatory cytokines, effectively increasing survival via α7-nAChR." (PMID 40650213, 2025). "The primary signaling pathway activated by TLR2 and TLR4 in sepsis is the nuclear factor-kappa B (NF-κB) pathway." (PMID 40386784, 2025). "Since eCIRP, HMGB1, and histone H3 are the major DAMPs that promote inflammation via TLR4 in sepsis, we selected them as targets to be cleared from circulation." (PMID 40421030, 2025). "In inflammatory diseases like sepsis and atherosclerosis, inhibiting TLR-4 signal transduction effectively alleviates excessive inflammatory responses." (PMID 40404908, 2025). "Clinical studies have demonstrated that individuals with sepsis exhibit elevated mRNA expression of TLR4, alongside with an upregulation of TLR2 receptor protein levels." (PMID 41268545, 2025). "Nano-curcumin alleviates sepsis-related inflammatory responses by inhibiting the TLR4 signaling pathway." (PMID 41041277, 2025). "For instance, TNFSF14 exacerbated sepsis‐related acute kidney injury via the TLR4/MyD88/NF‐κB pathway and activated the NFκB‐TLR3 pathway to induce acute hepatitis." (PMID 40768619, 2025). "Emerging evidence underscores the TLR4/NF-κB signaling axis as a central regulator of inflammatory pathologies, including chronic inflammation and sepsis." (PMID 40278266, 2025). "Ononin treatment ameliorated altered levels of oxidative stress and inflammatory cytokines in sepsis rats by promoting the TLR-4 pathway." (PMID 41221897, 2025). "Toll-like receptor 2 (TLR2) and TLR4 signaling pathways are pivotal to the pathogenesis of sepsis from the clinical data analysis." (PMID 40963927, 2025). "Despite contrasting findings, both studies highlight the regulatory influence of miRNAs on TLR4 signaling, underscoring a shared molecular axis in sepsis pathophysiology." (PMID 40927580, 2025).
Sepsis (continued). "Network pharmacology and molecular docking analysis suggested the involvement of TLR4/MAPK/NF-κB signaling pathway as a key mechanism by which 4-OI ameliorated sepsis-induced vascular cell inflammation and injury, which was confirmed by western blotting." (PMID 40524158, 2025). "While this response is critical for pathogen clearance, excessive activation of TLR4 contributes to the hyperinflammatory state observed in sepsis, exacerbating tissue damage and organ dysfunction." (PMID 40509176, 2025). "Some TLR-4 modulators, particularly those tested in sepsis treatment, have failed in clinical trials." (PMID 40404908, 2025). "NETs facilitate the advancement of intracoronary thrombus via the activation of the platelet TLR4 pathway, exhibiting mechanistic parallels with sepsis-induced disseminated intravascular coagulation." (PMID 41341291, 2025). "Our study reveals that miR-217 attenuates sepsis-induced liver injury by targeting TLR4, suggesting that TLR4 is involved in the modulation of LPS-induced liver injury." (PMID 39067063, 2025). "In mice with LPS-induced sepsis, myocardial TLR4 and JNK protein expression, plasma TNF-α and cTnI levels, and cardiac dysfunction are elevated." (PMID 40640887, 2025). "AQPs also influence key inflammatory pathways, including NF-κB and toll-like receptor 4 (TLR4), as well as the functions of macrophages and neutrophils during sepsis." (PMID 41488672, 2025). "Despite mechanistic evidence supporting TLR4’s role in thrombocytopenia in sepsis, clinical trials investigating its therapeutic potential remain lacking." (PMID 40003683, 2025). "We found that CASC7 contributes to sepsis-induced liver injury progression by targeting the miR-217/TLR4 axis." (PMID 39067063, 2025). "In the pathological process of sepsis, TLR4 and TLR2, as key members of the pattern recognition receptor family, play important roles in mediating the host immune response by virtue of their unique structural characteristics and ligand-binding mechanisms." (PMID 41041277, 2025). "The TLR4 signaling pathway, activated by bacterial endotoxins, is a major driver of inflammatory injury in sepsis, contributing to inflammasome activation and cell death." (PMID 40869248, 2025). "As MAP kinases are also activated by other pattern recognition receptors (PRRs), including the sepsis-relevant TLR4,57,59 one would expect them to be activated even after RAGE blockade if MG-AGEs were able to act via several of these receptors." (PMID 40107203, 2025). "TLR4 signaling is considered a key pathway in the pathophysiology of sepsis, mediating innate immune activation." (PMID 40779122, 2025). "Monocytes, macrophages, and microglia express PRRs such as TLR4, which identify PAMPs and DAMPs during sepsis, subsequently generating inflammatory cytokines and chemokines via intracellular signaling pathways." (PMID 41142251, 2025). "The somatic nuclear autoantigenic sperm protein (sNASP)/tumor necrosis factor receptor-associated factor 6 (TRAF6) axis plays a crucial role in regulating inflammatory responses during sepsis through Toll-like receptor 4 (TLR4) signaling." (PMID 40108019, 2025). "Here, we extend those findings by demonstrating that cilastatin also protects against sepsis-induced AKI via interference with the TLR4/MyD88/NF-κB and NLRP3 signaling pathways, resulting in improved survival." (PMID 40869248, 2025). "During sepsis, TLR2 and TLR4 recognize pathogen-associated molecular patterns (PAMPs) derived from invading microorganisms, such as lipopolysaccharide (LPS) from Gram-negative bacteria." (PMID 40386784, 2025). "The activation of mononuclear phagocytes in sepsis is primarily driven by recognizing microbial products through Toll-like receptors (TLRs) (e.g., endotoxin by TLR4)." (PMID 40236814, 2025).